CRP (C-reactive protein)
Diseases named in the same sentence as CRP in open-access papers (continued):
Sharing a sentence is not in itself a finding about the gene and the disease.
atherosclerosis (continued). "Leptin also stimulates the secretion of inflammatory markers such as CRP, TNF-α and IL-6, which are directly involved in the development of endothelial dysfunction and atherosclerosis." (PMID 27598978, 2017). "Acute phase complement proteins related to C-reactive protein (CRP) evolve in parallel during inflammatory states and are now known to play a role in type 2 diabetes, lipid metabolism, and atherosclerosis." (PMID 27493451, 2016). "The laboratory indices of microinflammation include elevated blood levels of CRP and some cytokines, mainly IL-6, IL-18, IL-10, and TNF-alpha, which correlated with acceleration of atherosclerosis." (PMID 26236736, 2015). "Several markers, such as high sensitivity C-reactive protein (hs-CRP), interleukin (IL)-6, IL-8, and serum albumin levels (S[Alb]), were frequently applied to evaluate malnutrition, inflammation and atherosclerosis (MIA) syndrome in chronic dialysis patients." (PMID 25793462, 2015). "In particular, the specificity of C-reactive protein (CRP) has been of concern because CRP has been found to be nonspecifically elevated in chronic inflammatory conditions, such as atherosclerosis and CKD." (PMID 25407928, 2014). "Previous studies have shown that β2GP I/oxLDL/C reactive protein (CRP) complexes can up-regulate the expression of p38MAPK, increasing the generation of atherosclerosis in diabetic mice." (PMID 25204377, 2014). "The purpose of our study was to investigate the value of Hs-CRP and ANP ratio (Hs-CRP/APN ratio) on evaluating atherosclerosis progression." (PMID 25070472, 2014). "High sensitivity C-reactive protein (Hs-CRP) and adiponectin (APN) are two critical cytokines and exert inverse effects on atherosclerosis initiation and progression." (PMID 25070472, 2014). "In the present study, the high-cholesterol diet not only increased proinflammatory cytokine and CRP levels in the blood, but also resulted in the development of early pathologic changes of NAFLD and atherosclerosis." (PMID 24901254, 2014). "The aims of this study were thus to evaluate levels of inflammatory markers of atherosclerosis, such as IL-6, TNF-α, CRP, and PTX-3 in a sample of OSA patients; to assess the correlation between carotid IMT and levels of these inflammatory markers." (PMID 24481114, 2014). "The process of PBMC migration into the vascular intima and transformation to foam cells, constitutes the early event of atherosclerosis and is regulated by plasma inflammatory cytokines, including MCP-1 and CRP." (PMID 23408783, 2013). "Powerful predictors of cardiovascular diseases, including serum C-reactive protein (CRP), homocysteine, folate and vitamin B12, have been validated to accelerate or inhibit the process of atherosclerosis in animal and epidemiological studies." (PMID 23451155, 2013). "Recently, some studies have revealed that serum CRP levels are biochemical markers of ACS, and a significant correlation between CRP level and the severity of atherosclerosis has been documented." (PMID 23009223, 2012). "In the atherosclerosis group there were significant increase between 0 times and end time for all ICAM-1, VCAM-1 and CRP." (PMID 21214952, 2011). "Proinflammatory cytokines, such as interleukin (IL)-1β, IL-6 and tumor necrosis factor (TNF)-α and the acute phase reactant C-reactive protein (CRP) have important effects in inflammation and atherosclerosis." (PMID 21695270, 2011). "However, the causality of the association between CRP and cardiovascular diseases is not undisputed as elevated CRP has also been suggested to be a marker of the extent of atherosclerosis or a marker for the inflammation activity rather than cause of cardiovascular disease." (PMID 20653951, 2010).
atherosclerosis (continued). "Hence, the currently available data implies that effects of fetuin-A may be of greater importance in the very early phases of atherosclerosis, a pattern known from other CHD risk factors, such as C-reactive protein or adiponectin, which seem to be better predictors in primary prevention." (PMID 20822519, 2010). "There is growing evidence that C-reactive protein (CRP), a peripheral marker of inflammation, is also a marker of generalized atherosclerosis." (PMID 19400931, 2009). "We found that recombinant CRP markedly increased the production of IL-6 and MCP-1, cytokines that are thought to be important in the pathogenesis of atherosclerosis." (PMID 20157364, 2008). "This elevated risk is not merely coincidental but stems from shared inflammatory pathways, including those involving CRP, RANKL, and the receptor for advanced glycation end products (RAGE), linking persistent systemic inflammation with vascular dysfunction and atherosclerosis." (PMID 40943152, 2025). "In addition, systemic inflammation (e.g., high CRP and/or IL-6 values) and infection from DFU drive endothelial dysfunction, accelerating atherosclerosis and renal damage." (PMID 40725102, 2025). "Persistent low-grade inflammation, characterized by moderate increases in circulating pro-inflammatory cytokines (C-reactive protein: CRP; interleukins (IL): IL-6, IL-2, IL-7, IL-8, etc.), plays a significant role in all atherosclerosis formation and progression phases." (PMID 40428891, 2025). "CRP is not only a non-specific marker of inflammation but also actively involved in CVD such as atherosclerosis and vascular inflammation, making it a strong predictor and risk factor for cardiovascular events." (PMID 41561801, 2025). "The median hs-CRP serum level in healthy controls was significantly lower than in psoriasis vulgaris patients without atherosclerosis (p < 0.05) but not in those with atherosclerosis (p > 0.05)." (PMID 39104857, 2024). "This study provides evidence of a direct relationship between periodontal microbiota and subclinical atherosclerosis, independent of CRP." (PMID 39610974, 2024). "Additionally, the reliance on different metrics to measure atherosclerosis, like CIMT, aPWV, CRP, and ESR can introduce variability in the results." (PMID 39739136, 2024). "It is believed that the ability of CRP to form connections with ox-LDL may become a key point in slowing down the formation of foam cells and, consequently, slowing down the process of atherosclerosis." (PMID 39329916, 2024). "Studies on the role of CRP in the relationship between subclinical hypothyroidism and atherosclerosis have not been conducted." (PMID 39687453, 2024). "Thus, inflammatory factors, such as C-reactive protein (CRP), interleukin (IL)-6, and tumor necrosis factor-α (TNF-α), are consistently elevated in atherosclerosis." (PMID 38699583, 2024). "Additionally, IL-6 induces the secretion of C-reactive protein (CRP), which further activates the complement system and induces monocytes to express tissue factor (TF), contributing to atherosclerosis." (PMID 39857599, 2024). "The high-sensitive (hs) C-reactive protein (hs-CRP) as a biomarker for atherosclerosis was not evaluated in this study." (PMID 39594152, 2024). "CRP has been a well-studied inflammatory marker in atherosclerosis but we found no significance of CRP in identifying recurrence." (PMID 39351476, 2024). "Clinical periodontal parameters, TNF-α and IL-8 in GCF and IL-17A, hs-CRP, and LDL in serum, had more significant predictive roles in developing subclinical atherosclerosis (IMT ≥ 0.75 mm) in comparison with other cytokines, fibrinogen, and other lipid status parameters." (PMID 36983201, 2023).
atherosclerosis (continued). "In a mouse model of atherosclerosis, it has been discovered that a CRP mutant, also known as non-native CRP, is atheroprotective." (PMID 37860004, 2023). "The current evidence indicatesthat CRP is more than an innocent bystander in atherosclerosis, and not just a“culprit”." (PMID 39077585, 2023). "did not prove a link between serum concentrations of atherosclerosis markers (brain natriuretic peptide, CRP and tumor necrosis factor-ɑ) and PTH or calcium levels." (PMID 37842310, 2023). "Several new anti-inflammatory and anti-cytokine agents, including but not limited to direct upstream inhibitors of the NLRP3 inflammasome, and natural inhibitors of IL-6, can be expected to be used in atherosclerosis by targeting the NLRP3, IL-1, IL-6 to CRP pathway." (PMID 36873405, 2023). "Regarding the relationship between CRP and vascular indicators of atherosclerosis in patients with advanced kidney disease, there is no consensus among authors in the literature: Some identified a relationship, while others did not." (PMID 37893519, 2023). "CRP has the capability to bind to LDL particles through its phosphocholine binding site, which contributes to the formation of foam cells and the development of atherosclerosis." (PMID 38074681, 2023). "We also corroborated results from other studies where serum CRP levels do not associate with adjusted risk of other CVD: myocardial infarction, coronary artery disease, heart failure, and atherosclerosis." (PMID 37298077, 2023). "The literature suggests that higher levels of some inflammatory markers, such as C-reactive protein (CRP), erythrocyte sedimentation rate (ESR), and fibrinogen, could represent the tip of the iceberg in the inflammatory process related to atherosclerosis." (PMID 36836178, 2023). "Sustained expression of Ref‐1 and CRP accumulation in the cytosol may inhibit STAT3/Ref‐1 interactions and increase the inflammatory response of CRP, thus accelerating atherosclerosis after radiotherapy." (PMID 35178859, 2022). "CRP induces a significant increase in the expression of intercellular adhesion molecule-1 (ICAM-1) and vascular cell adhesion molecule-1 (VCAM-1), which accelerates the inflammatory response in atherosclerosis." (PMID 36418968, 2022). "For example, low-dose methotrexate used in cardiovascular inflammatory reduction trial (CIRT) did not lower IL-1β, IL-6, CRP levels, or reduce cardiovascular events in patients with stable atherosclerosis." (PMID 36555898, 2022). "Plasma levels of ADM also positively correlate with levels of inflammatory markers such as CRP and IL-6, which could explain the relationship between ADM and both atherosclerosis and airflow obstruction/COPD." (PMID 35263363, 2022). "Increasing PA levels or CRP was not related to subclinical atherosclerosis, p > 0.09 (OR of 0.97; β = −0.034; p = 0.888)." (PMID 35627885, 2022). "Among patients with stable atherosclerosis, low-dose methotrexate did not reduce levels of interleukin-1β, interleukin-6, or CRP and did not result in fewer cardiovascular events than placebo." (PMID 36319655, 2022). "The MIS was positively correlated with age, the number of hospitalizations, the presence of atherosclerosis, ferritin, IL-6, TNF-α, CRP and MIAS and inversely correlated with the BMI, albumin, prealbumin, hemoglobin, transferrin, creatinine and blood phosphorus." (PMID 33413177, 2021). "Other animal models like e.g., transgenic rabbits expressing human CRP have been used but here most of the investigations focused on atherosclerosis and not on acute incidents." (PMID 33679775, 2021). "There was a negative association between serum hs-CRP level and CIMT as a measure of atherosclerosis in groups of depressed versus non-depressed patients." (PMID 35434159, 2021).
atherosclerosis (continued). "Furthermore, eGFR was significantly associated with subfebrility/fever, systemic inflammatory parameters (CRP, WBC count) hyperlipidemia and vascular complications (atherosclerosis, myocardial infarction, heart- and renal-failure)." (PMID 34485326, 2021). "As atherosclerosis, and therefore CAD, is an inflammatory process, the serum CRP level may correlate with the severity of atherosclerosis and the size of the atherosclerotic plaque." (PMID 33453709, 2021). "In atherosclerotic lesions of human coronary arteries, a frequent co-localization of C-reactive protein (CRP) and of the TCC/C5b-9 has been observed, suggesting that CRP may be a mediator of atherosclerosis by activation of the complement system." (PMID 34649504, 2021). "On binary logistic regression analysis, CVDRF category, number of CVDRFs, VCI diameter, CRP and duration of illness were not significant predictors of atherosclerosis presence or a positive SE test." (PMID 34075600, 2021). "The level of CRP was higher in patients with atherosclerosis of two or three vascular beds compared to patients without atherosclerosis or atherosclerosis of one vascular bed." (PMID 33513851, 2021). "Levels of low-density lipoprotein (LDL), apolipoprotein B (ApoB), HDL, apolipoprotein A1 (ApoA1), and C-reactive protein (CRP) are significant biomarkers of vascular inflammation and are critical to almost all inflammatory disease processes including atherosclerosis." (PMID 33644628, 2021). "The study of C-reactive protein (CRP), interleukin (IL)-1β, and NLR family pyrin domain-containing 3 (NLRP3) inflammasome has revealed critical roles for each in post-infarction systemic inflammation and progression of atherosclerosis." (PMID 34685553, 2021). "In the inflammation part, TMAO could induce the expression of IL-1, TNF-α, C-reactive protein (CRP) via mitogen-activated protein kinase (MAPK), and NF-kappa B (NF-κB) signaling to promote the formation of atherosclerosis." (PMID 34414217, 2021). "Besides lowering the LDL concentration, statins also affect other pathways related to atherosclerosis, that is increase NO production, decrease ICAM-1 expression, and decrease CRP level." (PMID 34201137, 2021). "According to this distribution, the association of inflammation with clinical atherosclerosis manifestations was increased when evaluating SDF1 and CRP as a combined variable, regardless of the tested model." (PMID 34062730, 2021). "Patients with clinical atherosclerosis showed increased levels of SDF1 (2.7 ± 0.9 ng/mL vs. 2.3 ± 0.5 ng/mL, p < 0.001), MMP12 (501 pg/mL vs. 358.5 [241.5–553.5] pg/mL, p = 0.002) and CRP (0.24 [0.13–1] mg/dL vs. 0.12 [0.07–0.31] mg/dL, p < 0.001)." (PMID 34062730, 2021). "Third, statins can affect the inflammatory process in atherosclerosis, which is one of the important effects of statin, but inflammatory marker such as high sensitivity C-reactive protein was not measured in this study." (PMID 33481866, 2021). "Furthermore CRP and serum albumin can be used in follow-up and determining the prediction of the CAC score and atherosclerosis." (PMID 34445853, 2021). "MR studies showed that IL6 and CRP are causal for the development of atherosclerosis and CAD, but there are no studies on the role of IL6 as a risk factor for T2D, and CRP has not been demonstrated to be causal for the risk of T2D." (PMID 34677406, 2021). "It was found that, in patients with CAE without atherosclerosis, hs-CRP levels are elevated compared to normal coronaries." (PMID 34236824, 2021). "In addition to CRP, there are other pentraxins that have been suggested to play a role in the pathogenesis of at least AMD, atherosclerosis, and Alzheimer’s disease." (PMID 33363547, 2020). "IL-1β, IL-6, IL-18, c-reactive protein (CPR), tumor necrosis factor α (TNF-α), etc., as important proinflammatory factors in the process of atherosclerosis, play an important role in promoting the formation of atherosclerosis." (PMID 32733941, 2020).
atherosclerosis (continued). "The nonspecific inflammation factor C-reactive protein (CRP) is an important inflammatory factor in atherosclerosis." (PMID 32831861, 2020). "Briefly, as atherosclerosis progresses, increased secretion of tumor necrosis factor (TNF)-α and IL-1 induces production of IL-6 in activated monocytes and vascular smooth muscle cells, which enhances hepatic CRP synthesis." (PMID 32433661, 2020). "These suggestions are supported by the fact that, in rabbits, the inhibition of plasma CRP did not affect the development of atherosclerosis." (PMID 32849641, 2020). "Indeed, in one study, monomeric CRP, that is also capable of binding to atherogenic LDL, was employed and the results showed that monomeric CRP was protective against atherosclerosis in apoE−/− mice." (PMID 32849641, 2020). "In addition, elevated levels of C-Reactive Protein (CRP), homocysteine, lipoprotein (a), and fibrinogen can be observed in the blood of patients with atherosclerosis." (PMID 31336615, 2019). "Consistent with this hypothesis, a CRP molecule which was modified in vitro and was capable of binding to atherogenic LDL, did reduce the development of atherosclerosis in mice." (PMID 31379851, 2019). "C-reactive protein is not present in the healthy vessel wall but it becomes detectable in the early stages of atherogenesis and accumulates during the progression of atherosclerosis." (PMID 30142970, 2018). "In SLE, aspirin did not alter the level of several atherosclerosis biomarkers (homocysteine, high-sensitivity CRP, soluble VCAM-1, P-selectin, and thrombomodulin)." (PMID 29435447, 2017). "Although the investigations on the interaction of CRP with lipid indicating a connection between CRP and atherosclerosis have started from early on in the laboratory 12, no data have been provided yet to link CRP, PCSK9 and LDL uptake." (PMID 27633999, 2016). "As an example, a significant reduction of total cholesterol levels with atorvastatin failed to halt progression of atherosclerosis or to decrease inflammatory markers such as C-reactive protein (CRP) in SLE patients." (PMID 28038677, 2016). "In rabbits with induced atherosclerosis and chronic arthritis, treatment with G inhibited NF-κB activation and down-regulated COX-2 expression in peripheral blood mononuclear cells, while also decreasing circulating levels of CRP and IL-6." (PMID 25719429, 2015). "Initiation of inflamm-atory mediators, such as C-reactive protein (CRP), IL-6, and tumor necrosis factor could be considered as a further role of Ox-LDL in atherosclerosis." (PMID 25864817, 2015). "Atherosclerosis is a hyperlipidemia-induced chronic inflammatory process of the arterial wall, involving interleukins (ILs) such as IL-1β, IL-6, tumor necrosis factor (TNF)-α, and C-reactive protein (CRP)." (PMID 25664324, 2015). "C-reactive protein (CRP) is an acute-phase reactant and a marker for underlying systemic inflammation, irrespective of its etiology, also reflecting atherosclerosis and plaque rupture, when applying high sensitivity CRP assays." (PMID 26664888, 2015). "C-reactive protein (CRP) is a biomarker of inflammation with predictive value for cardiac events in both, apparently healthy subjects and patients with coronary artery disease (CAD), a cardiac manifestation of atherosclerosis." (PMID 26473826, 2015). "C-reactive protein (CRP), an indicator of systemic inflammation, may predict the burden of atherosclerosis." (PMID 25191699, 2014). "CRP mutants (nonnative CRP) capable of efficiently binding to all forms of atherogenic LDL can be evaluated for their effects on the development of atherosclerosis in available animal models to test our conclusion." (PMID 24948846, 2014). "In this study, intensive pitavastatin therapy also showed more favorable effects in reducing the inflammatory or oxidative response, assessed by C reactive protein and MDA-LDL levels, which may play a pivotal role in all stages of atherosclerosis." (PMID 24586502, 2014).